SLAMF7 (SLAM family member 7)
Diseases named in the same sentence as SLAMF7 in open-access papers (continued):
Sharing a sentence is not in itself a finding about the gene and the disease.
myeloma (continued). "In previous studies, the cell-surface glycoprotein, CS1 (CD2 subset 1, CRACC, SLAMF7, CD319, or 19A24), is universally and highly expressed in normal plasma cells and myeloma cells." (PMID 33330069, 2020). "A humanised Ab to SLAMF7, HuLuc63, exhibited NK-mediated ADCC of primary myeloma cells in vitro and anti-tumour activity in vivo that was depended on NK cells and Fc-CD16 interactions." (PMID 30626155, 2019). "Elotuzumab is a humanized IgG1 mAb that induces NK cell activation by binding to SLAM family member 7 (SLAMF7) (also known as CS1), which is highly expressed on NK cells, plasma cells, and myeloma cells (>95%)." (PMID 31569769, 2019). "There are various ongoing clinical trials using CAR T cell technology to target myeloma antigens such as B cell maturation antigen (BCMA), CD138, CS1 glycoprotein antigen (SLAMF7) and immunoglobulin light chains." (PMID 31684964, 2019). "Similar to SLAMF2 and SLAMF7, SLAMF6 is highly expressed on myeloma cells from NDMM and RRMM patients." (PMID 31842518, 2019). "In some preclinical studies, SLAMF7 was targeted by humanized mAb, HuLuc63 (Elotuzumab), which stained CD138+ myeloma cells, NK cells, NK-like T cells, and CD8+ T cells." (PMID 29662641, 2018). "Hsi and colleagues detected high levels of SLAMF7 mRNA in CD138+ plasma cells from healthy donors, patients with MGUS, smoldering myeloma and newly diagnosed patients, whereas NK cells expressed a substantially lower level of SLAMF7 mRNA." (PMID 30455698, 2018). "The signaling lymphocytic activation molecule family (SLAMF7; also known as CS1 or CD319) is highly expressed on plasma cells from multiple myeloma (MM) as well as natural killer (NK) cells and is a well-known therapeutic target of elotuzumab." (PMID 30410677, 2018). "In 2015, the U.S. Food and Drug Administration (FDA) approved three new therapies for multiple myeloma, namely Ixazomib (an oral proteasome inhibitor), Daratumumab and Elotuzumab (monoclonal antibodies against CD38 and SLAMF7 respectively)." (PMID 27863374, 2017). "SLAMF7 is targeted by the recently FDA-approved cancer drug, Elotuzumab, a humanized monoclonal antibody prescribed for relapsed or refractory multiple myeloma." (PMID 28240269, 2017). "mAbs against interleukin-6, B-cell activating factor CD138, Dickkopf 1 (DKK1), receptor activator of nuclear factor-κB ligand (RANKL), SLAMF7, and CD38 are currently in clinical development for the treatment of multiple myeloma." (PMID 28454113, 2017). "SLAMF7 expression on myeloma cells is consistently high and is not affected by cytogenetic abnormalities, genomic mutations, or disease stage." (PMID 41228264, 2025). "Additionally, SLAMF7‐CAR‐T cells can target both CAFs and multiple myeloma cells, though SLAMF7's expression on other lymphoid cells raises off‐target toxicity concerns." (PMID 40888234, 2025). "In addition, screening of multiple myeloma surface antigens has identified other promising targets, including CD28 (Tp44), CD48 (BLAST), CD74 (CLIP), CD138 (SDC1), CD229 (SLAMF3), CD319 (SLAMF7), CCR10 (GPR2), TAC1 (NPK), TXNDC11, SLC1A5 (AAAT)." (PMID 41369346, 2025). "SLAMF7 is functionally important for plasma cell survival, and its discovery prompted development of the anti-SLAMF7 antibody elotuzumab, which is FDA-approved for administration in combination with lenalidomide and dexamethasone for the treatment of R/R myeloma." (PMID 38800372, 2024). "In ongoing clinical trial research (NCT03710421), SLAMF7-CAR T-cells have been engineered by incorporating an anti-SLAMF7 single-chain variable fragment (ScFv), memory-enriched T cells, and a truncated EGFR (EGFRt) molecule to target multiple myeloma cells." (PMID 38438559, 2024). "In this regard, potential therapeutic agents appear to be elotuzumab, targeting SLAMF7, which is expressed in myeloma cells and nonmalignant plasma cells, as well as activated DN2 cells and circulating antibody-secreting cells (ASCs), in human SLE." (PMID 37047548, 2023).
myeloma (continued). "Other distinct antigens in multiple myeloma include CD19 (the target of most CAR-T therapies in lymphoma), CD38 (the target of daratumumab and isatuximab), CS1/SLAMF7 (the target of elotuzumab), and GPRC5D (the target of the investigational bispecific antibody talquetamab)." (PMID 36505779, 2022). "Validating our strategy, we identified nearly all known canonical diagnostic markers and immunotherapeutic targets in myeloma, including BCMA, CD138/SDC1, CD38, CD56, SLAMF7/CS-1, CD46, Integrin-b7 (ITGB7), CD74/HLA-DR, TACI, CD48/ SLAMF2, and LY9/CD229." (PMID 36311892, 2022). "A significant negative correlation was noted between the expression of SLAMF7 on myeloma cells of the BM and SLAMF7 expression on either CD56dim or CD56bright NK cells in the peripheral blood of ND and RR patients." (PMID 33435153, 2021). "As SLAMF7 mediates myeloma cell adherence to the bone marrow, we hypothesized that SLAMF7 expression could be reduced in EMD and hence limit the efficacy of SLAMF7-directed therapy." (PMID 33575947, 2021). "Furthermore, trials with anti-BCMA CAR-T cells in earlier stages of the disease are ongoing and CAR-T cells targeting other multiple myeloma antigens such as CD38, CD138, and SLAMF7 are also being explored." (PMID 34572927, 2021). "SLAMF7 (also known as CS1 or CD319) stands for family member 7 (F7) of the signalling lymphocytic activation molecule (SLAM) family, a subset of the immunoglobulin superfamily of receptors expressed on several hematopoietic cells, including myeloma cells." (PMID 32138182, 2020). "Preliminary in vitro studies on the anti-SLAMF7 mAb, ELO, showed that the pre-treatment of either effector cells (peripheral blood mononuclear cells, PBMC) or target myeloma cells with clinically achievable doses of lenalidomide (LEN) enhanced ADCC-mediated lysis of MM cells triggered by ELO." (PMID 32899714, 2020). "The group additionally showed that SLAMF7 expression on myeloma cells was not affected in patients treated with bortezomib." (PMID 30455698, 2018). "These alternative mechanisms include promoting SLAMF7-SLAMF7 interactions between NK cells and myeloma cells, co-stimulating calcium signaling by other activating receptors in NK cells, and promoting ADCP of myeloma cells by macrophages." (PMID 30455698, 2018). "SLAMF7, also called CS1, is mainly expressed on multiple myeloma cells and NK cells." (PMID 30607140, 2018). "Importantly, BCMA has a more specific expression pattern when compared with the other multiple myeloma antigens CD38 and SLAMF7." (PMID 31548533, 2017). "Following the demonstration of promising preclinical and clinical activities, two monoclonal antibodies targeting CD38 (daratumumab) and SLAMF7 (elotuzumab) were approved by the Food and Drug Administration (FDA) to treat patients with relapsed and refractory multiple myeloma in late 2015." (PMID 31548533, 2017). "Similar results were obtained using other SLAMF7-positive myeloma cells, including IM-9, LP-1, and L363 cells (data not shown)." (PMID 25287778, 2015). "It is likely that enhanced activity in the model was due to increased NK cell activation through elotuzumab-mediated ADCC, which occurred via recruitment of effector NK cells into SLAMF7/CS1+ tumor xenografts and lenalidomide-mediated direct cytotoxic effects against myeloma cells." (PMID 25287778, 2015). "While we recognize that targeting SLAMF7 alone may not address all cases of myeloma, it represents a promising target that could complement therapies aimed at other markers." (PMID 40247106, 2025). "Overall, while the consequences of fratricide for anti-SLAMF7 CAR T cells and other immune cells require further investigation, these studies suggest that anti-SLAMF7 CAR T cells could be a promising therapeutic strategy for treating myeloma." (PMID 41228264, 2025). "Importantly, SLAMF7 is not found on normal tissues, making it an attractive target for immunotherapy in the treatment of multiple myeloma." (PMID 38961036, 2024).
myeloma (continued). "Since SLAMF7 is not exclusively expressed on myeloma cells, therapies targeting this antigen may also affect other cells expressing SLAMF7." (PMID 38438559, 2024). "While there is no EAT-2 in myeloma cells, SLAMF7 uses other mechanisms to promote survival." (PMID 37754488, 2023). "In addition, researchers have developed a new SLAMF 7 CAR-T product, which specifically targets SLAMF7 in both in vitro and mouse models by knocking out the SLAMF7 gene from T cells prior to the introduction of SLAMF7 CAR, effectively killing MM cell lines and primary human myeloma cells." (PMID 37158921, 2023). "However, we note that CCR10’s off-tumor expression profile is comparable to other clinically-investigated myeloma CAR-T targets SLAMF7 and CD138, and therefore is not anticipated to be particularly unfavorable." (PMID 35840578, 2022). "Immunohistochemical stainings to evaluate SLAMF7 expression in CD138+ myeloma cells documented strong and consistent SLAMF7 expression in all EMD and bone marrow biopsies, indicating a preserved expression of the antigen in myeloma cells even when located outside the bone marrow niche." (PMID 33575947, 2021). "It exerts its effect via a dual mechanism of action: direct activation of NK cells and ADCC via SLAMF7 ligation in which the Fc portion of elotuzumab binds to the activating Fc receptor (CD16) on NK cells, whereas the Fab portion of elotuzumab binds to SLAMF7 on myeloma cells." (PMID 32138182, 2020). "In addition, drugs with a different mechanism of action, such as the histone deacetylase inhibitor and the monoclonal antibodies (MoAb) targeting SLAMF7 or CD38, are a part of the anti-myeloma armamentarium and are very important for heavily pretreated or double refractory to a PI and IMiD patients." (PMID 31842517, 2019). "Identification of CD38 and SLAMF7 as suitable therapeutic targets because of their high expression on the surfaces of malignant plasma cells led to the development of daratumumab and elotuzumab, respectively, both of which received FDA approval as anti-myeloma agents three years ago." (PMID 30544512, 2018). "Moreover, Elotuzumab, promoted the ligation between NK and myeloma cells by the intermediary of SLAMF7 and induced NK cytotoxicity against myeloma cells independent of ADCC." (PMID 29662641, 2018). "This is important, since it suggests that Elo binding to SLAMF7 on the surface of NK cells (as would occur in treated patients) can co-stimulate calcium signaling responses triggered by NKp46 and other ITAM-coupled receptors engaging with ligands on the surface of myeloma cells." (PMID 30455698, 2018). "Importantly, >90% of patients with myeloma cells expressed SLAMF7 messenger RNA (mRNA) and protein, regardless of disease status and treatments." (PMID 31548533, 2017). "Although plasma cells do not express EAT-2, SLAMF7 may utilize other mechanisms to promote myeloma cell growth and survival." (PMID 27417553, 2016). "However, in this specific co-culture system, any bridging of SLAMF7 between effector and target cells was not sufficient to induce NK cell activation and myeloma cell killing." (PMID 25287778, 2015). "Taking these studies together, while the consequences of fratricide of both anti-SLAMF7 CAR T cells and other immune cells require further investigation, it appears that anti-SLAMF7 CAR T cells could be a promising therapeutic strategy for the treatment of myeloma." (PMID 38800372, 2024). "Due to their relevance in patients with MM, we analyzed SLAMF7 expression on this phenotype during an induction therapy with lenalidomide, dexamethasone, and bortezomib with or without elotuzumab within the German Speaking Myeloma Multicenter Group (GMMG) HD6 clinical trial." (PMID 33597728, 2021). "This lack of EAT-2 suggested that SLAMF7 may function as an inhibitory receptor in myeloma cells." (PMID 30455698, 2018).
myeloma (continued). "Interestingly, the anti-SLAMF7 antibody-elotuzumab has been approved for use by Food and Drug Administration (FDA), and enhances natural killer cell activation and cancer cell killing through interleukin-2 and TNF-α pathways, significantly improving progression-free survival of multiple myeloma." (PMID 28099903, 2017). "Only Ad[CE1A] significantly increased myeloma cell death, not Ad[PSA], providing evidence that cell death is due to SLAMF7-replication and not initial viral infection/load." (PMID 40247106, 2025). "While TNFRSF17 (BCMA) was highly specific for myeloma samples, other immunotherapy targets such as CD38, CD138 (SDC1) and SLAMF7 were not or only moderately higher expressed in MM versus healthy plasma cells." (PMID 38942927, 2024). "CS1 (SLAMF7, CRACC) is a rational target for myeloma CAR-T therapy since expression of CS1 is uniformly high on myeloma cells independent of cytogenetic abnormalities, genomic mutations, or disease stage." (PMID 35422095, 2022). "SLAMF7 (also known as CS1, CRACC, or CD319) is highly expressed in myeloma cells but is either less strongly or not expressed by normal hematopoietic stem cells." (PMID 36421358, 2022). "As previously shown for NKG2D, these results suggest that the expression of SLAMF7, NKG2D, and GITR may be downregulated when they encounter high levels of their ligands on myeloma cells or perhaps soluble ligands shed from tumors (not measured in this study)." (PMID 33435153, 2021). "Of note, although for DLBCL the expression of SLAMF7 does not impact on phagocytosis upon CD47-targeting treatment, its impact especially in multiple myeloma (MM) may well be different." (PMID 30710089, 2019). "In addition, SLAMF7 was highly expressed in plasma cells from healthy donors, patients with monoclonal gammopathy of undetermined significance (MGUS), smoldering multiple myeloma (SMM), and MM regardless of molecular subtype." (PMID 27417553, 2016). "However, incorporating MM antigens that are not exclusive to plasma cells and myeloma cells, particularly those strongly expressed on MM cells but with lower expression on healthy cells (e.g., CD138, CD38, and SLAMF7), can offer advantages and open new possibilities." (PMID 38438559, 2024). "Interestingly, SLAMF7 expression was observed in normal and neoplastic plasma cells in nearly all patients with monoclonal gammopathies of undetermined significance (MGUS), smouldering myeloma and multiple myeloma, but not in normal tissues or a variety of solid tumours." (PMID 30626155, 2019). "Thus, SLAMF7 does not have activation or inhibitory signaling function in myeloma cells, due to the lack of EAT-2 to mediate activation and the lack of CD45 to maintain Src family kinases in an active state that is required to phosphorylate SLAMF7 and the inhibitory SHIP-1 phosphatase." (PMID 30455698, 2018).
multiple myeloma (70 papers, 2013 to 2026). "SLAMF7, CD20, and CD52 were expressed in 98%, 38%, and 25% of AL amyloidosis cases with light chain‐restricted PCs as the amyloidogenic clone, respectively." (PMID 27109862, 2016).
rheumatoid arthritis (9 papers, 2013 to 2025). A chronic, systemic autoimmune disorder characterized by inflammation in the synovial membranes and articular surfaces. "SLAMF7 has also been suggested as a possible therapeutic target for rheumatoid arthritis, a disease more common in smokers." (PMID 33593402, 2021). "With the exception of IBD patients, the upregulated expression of SLAMF7 was detected in patients with acute and chronic inflammation, such as those with rheumatoid arthritis and COVID-19 pneumonia, indicating the extensive role of SLAMF7 in regulating the inflammatory response." (PMID 40646691, 2025). "More recently, SLAMF7/CD319 was also found to be differentially upregulated on monocytes from inflamed rheumatoid arthritis synovial tissue, as compared to osteoarthritis synovium; SLAMF7 signaling on these monocytes induced super-activation and inflammatory cytokine release." (PMID 33936082, 2021). "SLAMF7 is selectively expressed by macrophages from sites of inflammation and is regulated by IFN-γ in rheumatoid arthritis, inflammatory bowel disease, and COVID-19 pneumonia." (PMID 40455785, 2025). "A study of rheumatoid arthritis single-cell RNA sequencing data demonstrated that five genes, KLRG1, CRTAM, SLAMF7, PTPN2, and KLRD1, were downregulated in activated and effector T cells isolated from synovial fluids." (PMID 38254179, 2024).
autoimmune disease (7 papers, 2013 to 2025). A disorder resulting from loss of function or tissue destruction of an organ or multiple organs, arising from humoral or cellular immune responses of the individual to their own tissue constituents. "This work discovered genetic variations in KLRG1, CRTAM, SLAMF7, PTPN2, and KLRD1, which could be linked to altered PD-1-mediated cellular immune responses and may lead to autoimmune disorders." (PMID 38254179, 2024). "Interestingly, low KLRG1, PTPN2, and SLAMF7 levels have been observed in many autoimmune diseases, usually in the context of tissue-resident T cells." (PMID 38254179, 2024). "This provides a mechanistic explanation for the genetic association between a SNP in the SLAMF7 promoter and susceptibility to MS, and provides a foundation on which future studies aimed at modulating SLAM family receptors to treat autoimmune diseases may build from." (PMID 36199066, 2022). "On the other hand, cluster 7 cells displayed uniquely high expression of Slamf7, Eomes, and Gzmk, and as such, cells within this cluster bore a resemblance to a cytolytic CD4+ T cell subset that has been identified in tumors as well as autoimmune disease." (PMID 36255051, 2022).
systemic lupus erythematosus (7 papers, 2013 to 2025). An autoimmune multi-organ disease typically associated with vasculopathy and autoantibody production. "Our study also revealed a striking loss of CD8 T cells expressing SLAMF3, SLAMF5 or SLAMF7 in the lupus patients in clinical remission." (PMID 28387859, 2017). "We identified a selective loss of CD8 T cells expressing SLAMF3, SLAMF5 or SLAMF7 in the lupus patients in clinical remission." (PMID 28387859, 2017). "In contrast, the proportion of CD8 T cells expressing SLAMF3, SLAMF5 or SLAMF7 was significantly lower in the lupus patients in clinical remission compared with the other two groups." (PMID 28387859, 2017). "In contrast, changes in the frequency of the SLAMF2-, SLAMF4- and SLAMF7-positive DN T cells, which share a gene expression profile with the CD8 T cells, distinguished the lupus patients from healthy controls." (PMID 28387859, 2017). "Changes in the frequency of DN T cells positive for SLAMF2, SLAMF4 and SLAMF7 were observed in lupus patients irrespective of the disease activity." (PMID 28387859, 2017). "Although the DN T-cell population was not expanded in our SLE cohort, the proportions of SLAMF2-, SLAMF4- and SLAMF7-expressing cells were significantly different in the lupus patients, regardless of the disease activity, compared with the healthy controls." (PMID 28387859, 2017).